TNF (tumor necrosis factor)
Diseases named in the same sentence as TNF in open-access papers (continued):
Sharing a sentence is not in itself a finding about the gene and the disease.
glaucoma (continued). "The neutralization of the actions of TNF and interleukin-1β (IL-1β) in the retinal organotypic cultures was able to prevent the loss of RGCs triggered by EHP, reinforcing the role of retinal inflammation in neurodegeneration in glaucoma." (PMID 32218163, 2020). "Therefore, an increase was shown in the expression of genes responsible for the initiation of inflammation such as the Toll-like receptor (TLR) and purinergic P2 receptors (P2X7), or for amplifiers of inflammation such as the TNFα gene in glaucoma patients." (PMID 32106630, 2020). "We then examined the gene expression of several proinflammatory cytokines (TNFα, IL-1β, IL-6, and IL-18) and chemokines (MIP-1α, MIP-1β, MIP-2, MCPI, and IP10) that have been implicated in human and experimental models of glaucoma." (PMID 31570110, 2019). "Moreover, both TNF-α and its receptor TNF-R1 are upregulated in glaucomatous retinas in the RGCs and retinal glial cells, respectively, suggesting a direct contribution of the TNF-α signaling cascade in optic nerve degeneration in glaucoma." (PMID 31481963, 2019). "Moreover, blocking microglia activation with minocycline or anti-TNFα prevents the infiltration of immune cells and significantly reduces axon degeneration and death of RGCs in experimental models of glaucoma." (PMID 31570110, 2019). "It is possible that glaucoma might induce TNFα production through a different signaling pathway than that activated by lipopolysaccharide." (PMID 26876380, 2016). "In both experimental and human glaucoma, in addition to TNF-α, astrocytes can produce and/or respond to other neurotoxic molecules such as NO, IL-6, and endothelins (ETs) which could directly damage RCG axons." (PMID 27294114, 2016). "The TNF is involved in certain types of glaucoma, and the TNF injection model may be useful in understanding the mechanism of axonal degeneration of RGCs." (PMID 25863674, 2015). "Anti-TNF drugs are neuroprotective in an animal model of glaucoma." (PMID 25875446, 2015). "TNF is involved in certain types of glaucoma, and the TNF injection model may be useful in understanding the mechanism of axonal degeneration of RGCs." (PMID 26578885, 2015). "Tumor Necrosis Factor (TNF) mediates retinal ganglion cell death in glaucoma." (PMID 25875446, 2015). "Different types of monoclonal antibodies against TNFα, such as Infliximab, Adalimumab, Certolizumab pegol and Golimumab, or circulating receptor fusion protein, such as Etanercept, have been used to treat glaucoma, ischemic retinopathy or AMD." (PMID 25301432, 2014). "One of the cytokines consistently linked to glaucoma and RGC damage has been TNFα." (PMID 25407441, 2014). "Astrocytes are known to influence RGC health in glaucoma through increased reactivity that leads to production of both neuroprotective and neurodestructive factors, including brain-derived neurotrophic factor, tumor necrosis factor alpha and nitric oxide." (PMID 25133067, 2014). "Our results showed a significant increase in the production of nitrotyrosine and TNF-α in tissue lysates of glaucoma retinas compared with those of normal controls, whereas treatment with rapamycin significantly decreased the local production of these neurotoxic mediators." (PMID 24923557, 2014). "In recent years, it has been suggested that TNF-α may participate in apoptotic death of retinal ganglion cells in glaucoma patients." (PMID 24063017, 2013). "Accumulating studies strongly support the involvement of TNF-α in the etiology of glaucoma." (PMID 23559847, 2013). "Furthermore, to investigate the roles of TNF-α and risks of glaucoma, several recent studies detected the TNF-α level in the aqueous humor (AH) in patients with glaucoma and the control subjects." (PMID 23559847, 2013).
glaucoma (continued). "An increased protein level was measureable for TNF-α (TNF-α: ctrl = 538±200 U, glaucoma = 907±454 U; p = 0.13) and the interleukins IL-1ß (IL-1β: ctrl = 11262±2590 U, glaucoma = 15625±4194 U; p = 0.08) and IL-6 (IL-6: ctrl = 8301±2287 U, glaucoma = 12073±6695 U; p = 0.26)." (PMID 23451242, 2013). "One in vitro study provided evidence that mitochondrial dysfunction accompanying RGC death may be induced by glaucoma-related stimuli such as tumor necrosis factor (TNF)-α and hypoxia." (PMID 22737394, 2012). "Taken together, the results indicate that TNF released from glial cells may play a pivotal role in axonal degeneration in glaucoma." (PMID 23316132, 2012). "In conclusion, our results suggest that elevation of the pro-inflammatory cytokine TNF-α and ONH inflammation play an important role in linking elevated intraocular pressure to the loss of optic nerve axons and RGCs that are the hallmark features of glaucoma." (PMID 22802951, 2012). "Data from clinical studies and animal models of induced elevated intraocular pressure (IOP) support the hypothesis that there is an inflammatory component to glaucoma and that TNFα contributes to disease progression." (PMID 21479271, 2011). "Moreover, it has been observed that anti-TNF-α antibodies can prevent death of RGCs by reducing ocular hypertension, suggesting that reducing the expression of TNF-α would be beneficial in treating glaucoma." (PMID 20029655, 2009). "Moreover, on the molecular level, LUT-EX@MN arrays reversed glaucoma-induced biochemical changes, such as the inflammatory markers; TNF-α, IL-8, and IL-1β, glaucoma-related biomarkers; MYOC, NRF2, and TIMP1 and the activity of glutathione peroxidase to levels comparable to healthy controls." (PMID 40643885, 2026). "Neurodegeneration in glaucoma might result from interactions between T cells and microglia that they activate, leading to the release of substances harmful to RGCs, such as TNF-α and nitric oxide synthase-2, as validated in both rodent models and human post-mortem glaucoma tissues." (PMID 41403938, 2025). "Not only severe trauma but also less invasive standard corneal surgery (PK, KPro, laceration repair, etc.)can lead to some rapid upregulation of TNF-α in the eye and ganglion cell apoptosis, which may, at least in part, contribute to subsequent secondary glaucoma." (PMID 37803488, 2024). "In that case, TNF-α blockers might be effective in the treatment of glaucoma." (PMID 39150567, 2024). "Thus, TNF-α appears to be an important potential therapeutic target for glaucoma." (PMID 38983051, 2023). "Furthermore, nitric oxide, tumor necrosis factor alpha (TNFα), glutamate and other toxic substances released from glial cells in glaucoma are considered a possible path that leads to RGCs’ death due to a compromised energetic state when mitochondria are unable to maintain their expected function." (PMID 37566048, 2023). "Additionally, IL-18 and TNFα were higher in patients with glaucoma compared to the ‘POH group’." (PMID 35998207, 2022). "Additionally, we have shown that SNC-121 treatment for 7 days reduces the production of pro-inflammatory cytokine (TNF-α), improved RGC function (as measured by Pattern ERGs), and reduced the loss of RGC numbers (as measured by retrograde labeling of RGCs) in rat glaucoma model." (PMID 33628191, 2021). "TNF-α-induced RGC death in glaucoma could be mediated by multiple pathways." (PMID 34419081, 2021). "Although IL-1α, TNF-α, and C1q have been independently implicated in glaucoma, it is not known whether they act in concert to induce A1 astrocyte reactivity in glaucomatous retinas." (PMID 33147455, 2020). "The anti-TrkC.T1 mAbs may be developed further as antagonists or may be used to eliminate TrkC.T1-expressing cells (which produce TNF-α) at the onset of degenerative diseases such as glaucoma, retinitis pigmentosa, and ALS (e.g., Müller glial cells in the retina or activated glia in spinal cord)." (PMID 32829283, 2020).
glaucoma (continued). "Interestingly, it is possible that ASK1 deletion may also have indirect effects on RGC survival, such as by reducing TNF-α production by macrophages, microglia and astrocytes, in which TNF-α is reported to mediate neurodegeneration in glaucoma." (PMID 32947996, 2020). "Using the microbead-induced mouse model of glaucoma, we also show an induction of genes associated with each of these pathways at 4 weeks post-microbead injection, specifically C3 and C1Q (complement cascade), TLR4 (Toll-like receptor pathway), TNFα (TNFα pathway), and NLRP3 (inflammasome pathway)." (PMID 31570110, 2019). "Moreover, use of bupropion, which suppresses TNFα production, significantly lowered the risk of developing POAG in humans in a large retrospective study, while anti-TNFα medication (etanercept) was found to be neuroprotective in a rodent model of glaucoma." (PMID 26903709, 2016). "Glial production of TNF and expression of its death receptor (TNF receptor-1, TNF-R1) on RGCs and their axons are known to be upregulated in the retina and optic nerve of glaucoma patients and animals with experimentally induced glaucoma and may induce RGC death via multiple mechanisms." (PMID 26451076, 2015). "There is evidence that the TNF-α protein may act to promote the development of β-amyloid deposits in Alzheimer patients, and McKinnon and colleagues have demonstrated evidence of build up of β-amyloid in retinal ganglion cells in a rat glaucoma model." (PMID 22509108, 2012). "Therefore, changes in MMP and/or TIMP expression triggered by TNFα or other factors induced by elevated IOP may be critical in regulating the ratio of soluble to membrane FasL expressed by microglia during glaucoma." (PMID 21479271, 2011). "An increased prevalence of the TNF-α −308 A-allele was reported in patients with primary open-angle glaucoma in a Chinese study, albeit this result could not be replicated in subsequent studies." (PMID 19279689, 2009). "In this 24-month prospective longitudinal observational cohort, 57 participants (19 controls, 19 prostaglandin-treated glaucoma, 19 untreated glaucoma) underwent spectral-domain OCT, validated sleep assessment, and serial IL-6 and TNF-α profiling." (PMID 41683759, 2026). "Inflammatory cytokines, such as TNF-α, IL-1β and IL-6, have been identified to clearly contribute to RGC death in glaucoma." (PMID 40528237, 2025). "It was found that multiple inflammatory factors like Tumor Necrosis factor alpha (TNF – α), Interleukin-6 (IL-6), and Interleukin-1 (IL–1) are abnormal in glaucoma patients’ intraocular fluid." (PMID 40486511, 2025). "The pro-inflammatory cytokine TNF-α induces NOX2-dependent ROS production in microglia and has been identified in the aqueous humor of glaucoma patients." (PMID 40457155, 2025). "Experimental glaucoma models have shown that GLP-1RA suppresses interleukin-1α production, tumor necrosis factor α production, astrocyte transformation, and the subsequent death of retinal ganglion cells." (PMID 38250602, 2024). "Amongst the factors released by actuated microglia, TNF-α and IL-1β play crucial roles in several models of RGC injury and the progression of clinical glaucoma." (PMID 39125762, 2024). "Thus, damaged RGCs may serve as direct targets of TNF-α in severe glaucoma." (PMID 39408817, 2024). "The link between inflammation and neurodegeneration is well documented, with inflammatory cytokines, such as TNF-α, promoting RGC death in conditions like glaucoma and retinal ischemia." (PMID 39769388, 2024). "A recent study indicates that TNF-α and transforming growth factor-β2 (TGF-β2) in the aqueous humor are higher in glaucoma-affected eyes compered to control cataract-affected eyes." (PMID 39408817, 2024). "Several cytokines and proteins, including transforming growth factor (TGF)-β, TNF-α, and monocyte chemotactic protein (MCP)-1, were found to be elevated in glaucoma patients." (PMID 38920659, 2024).
glaucoma (continued). "Elevated levels of TNFα, IFNγ, IL17A, and TGFβ are observed in PACG, which is in alignment with previous reports on glaucoma." (PMID 39184151, 2024). "For instance, several inflammatory cytokines and chemokines, i.e., IL-6, TNF, CXCL12, and CXCL8, showed elevated centrality values in various networks, evidencing the detrimental role of neuroinflammation in glaucoma." (PMID 39458974, 2024). "S100A9 has also been reported to regulate TNFα production by activating the TLR4 pathway in acute herpetic neuralgia, a possible target for glaucoma therapy." (PMID 39125762, 2024). "In summary, the molecular analysis revealed that the induction of glaucoma by microbead injection results in an increase in the expression levels of markers of damage (BAX, CD45, and TNFα) in the retina and optic nerve." (PMID 37111243, 2023). "Previous studies have shown increases in the glial production of TNF-α, and the upregulation of TNF-R1 in RGCs in the eyes of patients with glaucoma." (PMID 37242611, 2023). "Moreover, TNF-α-mediated cell death may lead to neurodegeneration in glaucoma." (PMID 37020269, 2023). "In the WT mice, molecular analysis of the right retina with microbead-induced glaucoma revealed increased expression of the following genes (mean ± SD): BAX 1.44 ± 0.58 fold; TNFα, 1.38 ± 0.32 fold; CD45, 5.45 ± 0.25 fold; STAT3, 2.15 ± 0.72 fold." (PMID 37111243, 2023). "In summary, our study showed that the expression levels of TNF-α, IL-2, IL-6, IL-8, BDNF, MMP-2, MCP-1, VEGF, IFN-γ, LT-α, bFGF, PDGF-AA, and TIMP-1 were different among the 3 types of glaucoma." (PMID 36254076, 2022). "This was done by suppressing TNF, the key player in inflammatory and apoptotic signaling at RGC, and axon injuries in in vivo models of glaucoma." (PMID 35651608, 2022). "The levels of TNF-α, MMP-2, MCP-1, IFN-γ, TIMP-1, IL-6, IL-8, VEGF, and LT-α were different among the three types of glaucoma." (PMID 36254076, 2022). "Several inflammatory molecules, such as tumor necrosis factor-alpha (TNF-α), nitric oxide, and vascular endothelial growth factor, are upregulated in glaucoma, and they can affect the optic axon." (PMID 36034713, 2022). "TNFα and IL-18 levels in AH were different among all three groups with the ‘glaucoma group’ having the highest levels followed by the ‘POH group’ and ‘normal group’ (TNFα p = .05 and IL-18 p = .02)." (PMID 35998207, 2022). "Similar conclusions were described by Kondkar, who observed that an elevated level of tumor necrosis factor alpha (TNF-α) can induce RGC apoptosis and plays a key role in glaucoma neurodegeneration." (PMID 34830671, 2021). "There is increasing evidence that the neuroinflammation induced by excessive TNF-α, which is released from activated retinal glial cells, has a critical role in the onset of RGC damage in glaucoma." (PMID 34789280, 2021). "Paschalis showed that increasing concentrations of TNF-α and its receptors (TNFR1 and TNFR2), observed after ocular injury, can contribute to progressive damage to the retina and subsequent glaucoma." (PMID 34830671, 2021). "Significantly higher serum levels of IL-4, IL-6, and IL-12 (p70), along with lower TNF-α, were determined in POAG patients compared to controls, suggesting abnormal immune environments contributing to glaucoma." (PMID 34439995, 2021). "In primary open angle glaucoma (POAG) eyes, the level of IL-12, IL-6, TNF-α, IL-8, IFN-γ were noted to be remarkably raised." (PMID 32117217, 2020). "Treatment with the GLP-1R agonist NLY01 reduced microglia/macrophage production of IL-1α, TNF-α, and C1q; decreased A1 astrocyte conversion; and protected against RGC death in this mouse model of glaucoma." (PMID 33147455, 2020). "When the intraocular pressure is too high, primary cilia shorten, promoting the expression of tumor necrosis factor α (TNF-α), and transforming growth factor β (TGF-β), thereby initiating the molecular mechanisms underpinning glaucoma." (PMID 32676032, 2020).
glaucoma (continued). "In a study using a glaucoma model with chronic elevation of IOP, upregulated TNF was shown to be significantly decreased following rapamycin treatment, providing RGC protection." (PMID 30190527, 2018). "The impact of the immunomodulatory and neurotoxic actions of TNF on RGC death was illustrated in several in vitro studies and experimental glaucoma models." (PMID 26451076, 2015). "To answer this question, we examined the effect of H2O2 and TNFα on OPTN oligomerization, since such stimuli have been proven to be increased in glaucoma patients and in turn contribute to retinal ganglion cells apoptosis." (PMID 24983867, 2014). "TNFα signals through TNFR1 and TNFR2, and following retinal ischemia and a mouse model of glaucoma, both receptors are upregulated in cells of the inner nuclear layer and GCL." (PMID 25407441, 2014). "We also examined the effect of optineurin on TNFα-induced NF-κB activation in a retinal ganglion cell line RGC-5, a neuronal cell line relevant for glaucoma." (PMID 21408173, 2011). "An increased expression of TNF-α can shift the balance toward TNF-R1 signaling, as seen in glaucoma, and thus promote retinal ganglion cell death." (PMID 20029655, 2009). "Finally, this study highlights that human glaucomatous retinas exhibit elevated levels of TNF and RIP3 mRNA and microglia infiltration, thus demonstrating the role of neuroinflammation in glaucoma pathogenesis." (PMID 39448868, 2025). "Here, no significant changes of TNF-α as well as its receptors TNF-receptor 1 + 2 were noted in all glaucoma mice." (PMID 38515755, 2024). "Reduced expression of genes involved in the pathogenesis of glaucoma was also observed, including chemokines and cytokines (GFAP, Caspase-8, TNFα, IL-1β, IL-6, IL-18, MIP-1α, MIP-1β, MIP-2, MCPI, and IP10), components of the complement cascade (C3, C1Q), Toll-like receptor pathway (TLR4)." (PMID 38562304, 2024). "TNF-alpha was more frequently detected in glaucoma patients compared to cataract patients with no glaucoma." (PMID 37511830, 2023). "In glaucoma patients, the TNF-α concentration in the anterior chamber is increased and the expression of TNF-α in retinal microglia and optic nerve astrocytes is elevated, while inhibition of TNF-α by drugs suppresses microglial activation, axonal degeneration and RGC loss." (PMID 38983051, 2023). "Both TNF-α and heat shock proteins (released from damaged, stressed, or dead cells) upregulate NOX activities and ROS production in microglia, which have been suggested to play a key role in the pathogenesis of glaucoma." (PMID 36837806, 2023). "Therefore, we simultaneously compared serum and aqueous levels of TNF-α, IL-2, TGF-β2 and IL-4 and investigated the possible effects of cytokine levels on clinical characteristics and postoperative outcomes in glaucoma patients." (PMID 37020269, 2023). "Importantly, the continuous secretion of SASP such as MCP1, TNF-α, CSF and IL6 accelerated the death of RGC, leading to the aggravation of glaucoma." (PMID 37525172, 2023). "If we could find out clinical factors related to TNF-α elevation in OAG patients, there is a possibility to use them as a biomarker to indicate neuroinflammatory mechanisms as a part of their glaucoma pathogenesis." (PMID 36079162, 2022). "Given that TNF is highly generated and expressed by retinal glial cells, this potent pro-inflammatory cytokine plays an essential role in promoting RGC apoptosis in glaucoma." (PMID 35651608, 2022). "Despite TNF being the subject of interest in ocular studies, investigation of their mechanism involved and their relevance on TNF antagonists in animal model glaucoma have not been thoroughly addressed so far." (PMID 35651608, 2022).